RXRG (retinoid X receptor gamma)
Description:
Receptor for retinoic acid. Retinoic acid receptors bind as heterodimers to their target response elements in response to their ligands, all-trans or 9-cis retinoic acid, and regulate gene expression in various biological processes. The RAR/RXR heterodimers bind to the retinoic acid response elements (RARE) composed of tandem 5'-AGGTCA-3' sites known as DR1-DR5. The high affinity ligand for RXRs is 9-cis retinoic acid (By similarity).
Synonyms: NR2B3; RXRgamma; RXR-gamma; RXRC
Tractability: Small molecule: an approved drug acts on it; a high-quality ligand is known; it has a high-quality binding pocket; it belongs to a druggable protein family. PROTAC: ubiquitination databases record sites on it; a small molecule that binds it is known.
Target class: Nuclear receptor; Nuclear hormone receptor subfamily 2 group B; Nuclear hormone receptor subfamily 2; Transcription factor; Nuclear hormone receptor subfamily 2 group B member 3
Chemical probes: JP3000, JP3000 (high quality), tretinoin
Gene: Protein-coding gene on chromosome 1 (165,400,922 to 165,445,355, reverse strand). Ensembl gene ENSG00000143171.
Subcellular location: Nucleus; Cytoplasm
Subcellular location (Human Protein Atlas): Nuclear bodies; Nucleoplasm
Pathways (Reactome):
Gene expression (Transcription): Nuclear Receptor transcription pathway
Signal Transduction: Signaling by Retinoic Acid
Gene Ontology:
Molecular function: molecular condensate scaffold activity; protein binding; sequence-specific double-stranded DNA binding; DNA-binding transcription factor activity, RNA polymerase II-specific; nuclear receptor activity; retinoic acid-responsive element binding; DNA binding; DNA-binding transcription factor activity; nuclear steroid receptor activity; sequence-specific DNA binding; zinc ion binding
Biological process: cell differentiation; nervous system development; positive regulation of transcription by RNA polymerase II; retinoic acid receptor signaling pathway; nuclear receptor-mediated steroid hormone signaling pathway; regulation of DNA-templated transcription
Cellular component: cytoplasm; nucleus; chromatin; nucleoplasm; RNA polymerase II transcription regulator complex
Genetic constraint (gnomAD): Loss-of-function variants: 17 observed, 47.02 expected, observed/expected ratio (o/e) 0.36, 90% interval 0.25 to 0.54. The upper end of that interval is the gene's LOEUF score, 0.54, which puts it in group 2 of 6, group 1 being the genes least tolerant of losing a copy. Missense variants: 450 observed, 592.72 expected, observed/expected ratio (o/e) 0.76, 90% interval 0.7 to 0.82. Synonymous variants: 223 observed, 220.54 expected, observed/expected ratio (o/e) 1.01, 90% interval 0.91 to 1.13.
Homologues: Orthologues: pig RXRG (98% identical), rabbit RXRG (97% identical), chimpanzee RXRG (97% identical), mouse Rxrg (97% identical), macaque RXRG (97% identical), rat Rxrg (96% identical), guinea pig RXRG (96% identical), dog RXRG (88% identical), tropical clawed frog rxrg (75% identical), zebrafish rxrgb (71% identical), Drosophila melanogaster usp (42% identical), Drosophila melanogaster Hnf4 (31% identical), and 28 more. Paralogues in human: RXRA (71% identical), RXRB (65% identical), NR2F1 (36% identical), NR2F2 (34% identical), NR2F6 (33% identical), HNF4G (33% identical), HNF4A (32% identical), NR2C2 (30% identical), NR2C1 (29% identical), NR2E3 (28% identical), NR2E1 (27% identical).
Diseases named in the same sentence as RXRG in open-access papers:
RXRG is named in the same sentence as 70 diseases in open-access papers, as found by Europe PMC text mining. Sharing a sentence is not in itself a finding about the gene and the disease. The quoted sentences say what the papers report.
breast carcinoma (10 papers, 2008 to 2025). "Supporting this, evaluation of the interaction between RXRG and ER level of expression (RXRG*ER) using the Cox regression model showed significant association with longer breast cancer-specific survival and distant metastasis-free interval (both p = 0.001)." (PMID 31558802, 2019). "In summary, high RXRG expression in breast cancer is associated with favourable prognostic parameters and is an independent prognostic factor with prolonged patient survival." (PMID 31558802, 2019). "Regarding the association with patient outcome, high-nuclear RXRG expression was associated with improved breast cancer-specific survival and a longer time to distant metastasis in the whole series and in ER-positive breast cancer." (PMID 31558802, 2019). "Subsequent hierarchical clustering suggested that a number of those genes (including PPARG, FGF2, APOB, CRHBP, CETP, and RXRG) were significantly associated with breast cancer that appeared repeatedly in different GO-terms." (PMID 21059268, 2010). "Expression analysis for RXRG mRNA using Breast Cancer Gene-Expression Miner v4.0 showed that high RXRG expression was associated with older age at diagnosis (n = 3600; p = 0.0082), lower histological tumour grade (n = 3518; p = 0.0024), ER-positive status (n = 5558; p = 0.029)." (PMID 31558802, 2019). "High expression of RXRG was associated with longer breast cancer-specific survival (p < 0.0001)." (PMID 31558802, 2019). "Two of our previous studies showed that when EGCG was given in association with a synthetic retinoid X receptor-γ (RXRγ) agonist named 6-OH-11-O-hydroxyphenanthrene (IIF) to breast carcinoma, cholangiocarcinoma and colorectal carcinoma cell lines, cytotoxicity increased." (PMID 28465354, 2017). "Nuclear RXRG expression was significantly associated with smaller tumour size (p = 0.036), lower grade (p < 0.001), lobular histology (p = 0.016), lower Nottingham Prognostic Index (p = 0.04) and longer breast cancer-specific survival (p < 0.001), and longer time to distant metastasis (p = 0.002)." (PMID 31558802, 2019). "Moreover, using the continuous H-score to assess the association between RXRG expression and the clinicopathological parameters, as well as other breast cancer-related biomarkers revealed similar significant association to those obtained with the categorised RXRG." (PMID 31558802, 2019). "Used off-label for lung and breast cancer and Kaposi’s sarcoma, bexarotene binds to RXRs (RXRα, RXRβ, and RXRγ), activating these ligand-activated transcription factors to regulate gene expression." (PMID 40334012, 2025). "RXRG protein is an independent predictor of breast cancer specific survival and distant metastasis-free survival." (PMID 35096840, 2021). "This study provides evidence for the prognostic value of RXRG in breast cancer particularly the ER-positive tumours." (PMID 31558802, 2019). "We next identified differential gene expression between patients with low versus high RXRG mRNA expression in the Nottingham primary operable breast cancer series, which were included in the METABRIC34 study (n = 150)." (PMID 31558802, 2019). "Primary breast cancer tissue microarrays (n = 923) were immuno-stained for RXRG protein and correlated with clinicopathological features, and patient outcome." (PMID 31558802, 2019). "Multivariate analysis demonstrated RXRG protein as an independent predictor of longer breast cancer-specific survival and distant metastasis-free survival." (PMID 31558802, 2019). "Steroid-Receptors, Heterodimeric-Receptors and the Lipid-sensors, Retinoid-X-Receptors (NR2B1/RXRα, NR2B2/RXRβ, NR2B3/RXRγ) are excluded from our analysis given the wealth of data on their therapeutic significance in breast-cancer." (PMID 26894976, 2016). "Similar findings have been reported for RXRG in breast cancer cells." (PMID 41439026, 2025).
breast carcinoma (continued). "In breast cancer, elevated Retinoid X Receptor Gamma (RXRG) levels in tumor cells correlate with better outcomes, especially in estrogen receptor (ER)-positive cases, suggesting RXRG as a prognostic marker for ER-positive breast cancer patients." (PMID 40334012, 2025). "Similarly, in ER-positive tumours, high RXRG levels were predictive of longer breast cancer-specific survival (p < 0.0001) and longer distant metastasis-free interval (p = 0.002)." (PMID 31558802, 2019). "Therefore, this study aimed to investigate the potential prognostic role of RXRG in breast cancer with a focus on the luminal ER-positive class." (PMID 31558802, 2019). "The interaction between RXRG, ER, and other nuclear receptors may explain the prognostic effect of RXRG in breast cancer." (PMID 31558802, 2019). "In triple-negative breast cancer and HER2+ phenotypes, RXRG expression was neither associated with breast cancer-specific survival nor with distant metastasis-free interval." (PMID 31558802, 2019). "Moreover, RXRG expression is significantly higher in breast cancer histologic subtypes with better prognosis such as invasive lobular carcinoma, in contrast to ductal or medullary-like tumours, which typically are associated with poorer outcomes." (PMID 31558802, 2019). "This study aims to explore the prognostic significance of RXRG in breast cancer." (PMID 31558802, 2019). "We investigated the effects of epigallocatechin-3-gallate (EGCG), the most active green tea catechin, in combination with 6-OH-11-O-hydroxyphenanthrene (IIF), a synthetic retinoid X receptor-γ (RXRγ) agonist, on three breast carcinoma cell lines: MCF-7, MCF-7TAM and MDA-MB-231." (PMID 28465354, 2017). "Despite these constraints, we found a number of biologically meaningful, differentially expressed genes related to HIST1, HIST2 proteins, and some other such as PPARG, FGF2, APOB, CRHBP, CETP, and RXRG in breast cancer tissue compared to corresponding adjacent normal breast tissue." (PMID 21059268, 2010). "Furthermore, assessment of RXRG mRNA levels using bc-GenExMiner and TCGA demonstrated that high RXRG mRNA expression is significantly associated with better tumour characteristics and longer event-free survival of breast cancer patients, which corroborates with RXRG protein expression." (PMID 31558802, 2019).
melanoma (9 papers, 2009 to 2023). A malignant, usually aggressive tumor composed of atypical, neoplastic melanocytes. "For RXRg (the main differentiator between melanomas and other cancers), top GO terms included numerous lipid and basal metabolism associated functions as expected, suggesting RXRg may be regulating these functions within a melanoma context." (PMID 26217306, 2015). "When the UM samples were clustered together with the previously published NCI-60 NR expression data, it was found that RXRg expression defined a “melanoma cluster,” which contained both UM and CM samples." (PMID 26217306, 2015). "First, in agreement with our past studies identifying RXRg as a CM-specific marker, we found that UM cells also exhibit high levels of RXRg expression, making it a universal biomarker for melanoma tumors." (PMID 26217306, 2015). "We demonstrated that UM (like CM) is distinguished from other cancer cell lines by high expression of RXRg, an NR that we previously reported separates melanomas from other cancers." (PMID 26217306, 2015). "For these analyses, we selected two liganded NRs (ERRa and RXRg) that are expressed across the melanoma panel and that correlated strongly with our qRT-PCR data for these same cell lines (r = 0.82 for ERRa and 0.7 for RXRg)." (PMID 26217306, 2015). "In this report, we have demonstrated for the first time that the combination of a rexinoid and TZD effectively inhibits growth of differentiated melanoma expressing PPARγ and RXRγ using an in vivo model." (PMID 19267912, 2009). "In addition, the NR-to-NR and NR-to-genome expression correlation analyses identified RXRγ as a potential driver for melanoma-specific signaling, and ERRα as the uveal-melanoma-specific NR." (PMID 26594199, 2015). "Specifically, RXRg controlled gene networks were identified that may drive melanoma-specific signaling and metabolism." (PMID 26217306, 2015). "Finally, we have demonstrated that a combination of a selective rexinoid and retinoid agonists has an additive effect on growth inhibition of a melanoma cell line expressing RARβ and RXRγ." (PMID 19267912, 2009). "In order to evaluate the phenotypic diversity of our samples, we mapped the expression profile of key melanoma cell-state regulatory genes such as the NGFR, RXRG, MITF, SOX10, SOX9 and AXL genes." (PMID 36765773, 2023). "Also, since this work has targeted building a single comprehensive model, it is likely that subtle cancer type specific relationships are not captured such as the relationship between RXRG expression and melanoma." (PMID 36809237, 2023).
non-small cell lung carcinoma (6 papers, 2013 to 2025). A group of at least three distinct histological types of lung cancer, including non-small cell squamous cell carcinoma, adenocarcinoma, and large cell carcinoma. "Its expression has been shown to be downregulated by epigenetic modification in non-small cell lung cancer and hence, RXRG is regarded as a tumor suppressor gene." (PMID 41439026, 2025). "A correlation between RXRγ upregulation and Gefitinib treatment has been previously indicated by the cooperative antitumor activity of the RXRγ-selective agonist Bexarotene and Gefitinib in preclinical models of non-small cell lung cancer." (PMID 31390799, 2019). "In particular, hypermethylation of PIK3R5, CDKN2A and two retinoid X receptors (RXRG and RXRG) occurred in a non-redundant manner in the non small cell lung cancer subtypes (Z score=2.82, empirical P<0.01)." (PMID 28581523, 2017).
retinoblastoma (6 papers, 2010 to 2025). A malignant tumor that originates in the nuclear layer of the retina. "MDM2 is intrinsically expressed at high levels in maturing human cone and retinoblastoma cells, which is regulated by cone transcription factor RXRγ." (PMID 32824373, 2020). "Retinoid X receptor gamma (RXRγ) and thyroid hormone receptor beta 2 (TRβ2), which are cone fate determinants, and M/L opsin are prominently produced in most retinoblastoma cells, agreeing with immunostaining of pRb-depleted cone cells of the normal retina." (PMID 32824373, 2020). "Similarly, retinoblastoma cell proliferation depends on RXRγ, TRβ2, MDM2, and MYCN, implying that intrinsic L/M-cone factors contribute to the oncogenic state." (PMID 40767624, 2025). "In most cases, well-known cell type markers were used to identify cell clusters, such as RXRG for cone precursors, MKI67 for retinoblastoma cells." (PMID 34815392, 2021). "In retinoblastoma cells, MDM2 transcription is in part driven by RXRγ, a cell lineage transcription factor in the cone precursor cell of origin, yet the basis for further MDM2 upregulation in retinoblastoma tumors has not been established." (PMID 33425720, 2020).
type 2 diabetes (5 papers, 2009 to 2021). "For example, a case-control study of 264 patients in Taiwan reported a significant association between rs1479355 SNP in the RXRG gene and type 2 diabetes." (PMID 34659944, 2021). "A similar investigation in this area showed that the single nucleotide polymorphism of RXRG rs3753898 might be related to the genetic susceptibility of type 2 diabetes." (PMID 34659944, 2021). "However, there are many evidences suggesting that RXRG variations in humans are associated with lipid metabolism, as well as with glucose and Type 2 diabetes." (PMID 20019805, 2009). "Several studies have shown a positive correlation between SNPs in the RXRG gene and type 2 diabetes." (PMID 34659944, 2021). "Further, studies have identified a human-specific subnetwork regulated by RXRG, which has been validated to play a different role in hyperlipidemia and type 2 diabetes between human and mouse." (PMID 31772600, 2019). "This study suggests that activation of the skeletalmuscle RXRγ is a novel therapeutic strategy to treat or prevent type 2diabetes." (PMID 21655215, 2011). "Also, meta-analysis of inter-species liver co-expression networks identified a human-specific sub-network regulated by RXRG, which has been validated to play a role in hyperlipidemia and type 2 diabetes." (PMID 24641809, 2014). "Finally, we identified a human-specific sub-network regulated by RXRG, which has been validated to play a different role in hyperlipidemia and Type 2 diabetes between human and mouse." (PMID 20019805, 2009). "Increasing RXRγ expression may be a novel therapeuticstrategy against type 2 diabetes." (PMID 21655215, 2011).
diabetes (4 papers, 2014 to 2025). "Thus, our study identifies RXRγ as a key target for the treatment of metabolic diseases such as obesity and diabetes." (PMID 40855678, 2025).
Obesity (4 papers, 2011 to 2025). Accumulation of substantial excess body fat. "Since RXRγ functions as a heterodimeric partner of PPARγ in adipose tissue, it is likely that these age/obesity-associated impairments in PPARγ would undermine RXRγ-PPARγ target gene activation, including UCP1." (PMID 40855678, 2025). "Complementary bioinformatics analysis revealed four key targets associated with obesity onset: HSD11B1, RXRG, G6PD and PIK3R1." (PMID 41032481, 2025). "The LASSO regression models were built from data from obese and normal tissues, and the λ analysis indicated that the model achieved optimal predictive accuracy for obesity at λ = 4, leading to the identification of 4 core diagnostic genes, including HSD11B1, RXRG, G6PD and PIK3R1." (PMID 41032481, 2025). "Although few studies have directly examined RXRγ in ageing or obesity, relevant evidence includes the finding that RXRγ-knockout mice are protected against high-fat diet – induced weight gain, implying that RXRγ may normally support lipid accumulation in obesogenic environments." (PMID 40855678, 2025). "Through the bioinformatics analysis, we identified HSD11B1, RXRG, G6PD, and PIK3R1 as core genes for the interplay between Crataegus pinnatifida and the obesity-related gut microbiota in obesity regulation." (PMID 41032481, 2025). "Taken together with our previousreport, thisstudy demonstrates that RXRγ mice do not develop insulin resistance despite highintramuscular lipids, and appear to be protected against obesity-inducedlipotoxicity in the skeletal muscle." (PMID 21655215, 2011).
thyroid cancer (4 papers, 2009 to 2025). "In the context of thyroid cancer, the upregulation of RXRG has been linked to tumor dedifferentiation and LNM." (PMID 40465540, 2025). "The results revealed that RXRG knockdown inhibited thyroid cancer cell proliferation and colony formations compared with the control." (PMID 40465540, 2025). "The effect of RXRG on the expression of these transcription factors in thyroid cancer cell lines was investigated." (PMID 40465540, 2025). "RXRG dysregulation may contribute to tumor dedifferentiation and metastatic progression in thyroid cancer, warranting systematic investigation." (PMID 40465540, 2025). "Further investigations should be envisaged to address the functional role of RXRG, VDR, and the thyroid hormone receptor in thyroid cancer, especially in FVPTCs." (PMID 25923053, 2015).
Anxiety (3 papers, 2015 to 2022). Intense feelings of nervousness, tension, or panic often arise in response to interpersonal stresses. "For example, the RARB:RXRG dimer’s activities in amygdala have been linked to expression of anxiety-related phenotypes, and RORA is associated with enhanced fear response in humans and mice." (PMID 35192674, 2022). "To assess effect of loss of RXRγ on anxiety, we compared the behavior of RXRγ knockout animals and wild type control siblings in a novel open field environment and in an elevated plus maze." (PMID 33692389, 2021). "We identify four genes (TNR, RXRG, MCTP1, and CMYA5) associated with anxiety in mice and risk of BD in humans." (PMID 26190982, 2015). "CMYA5, MCTP1, RXRG, and TNR are associated with mouse anxiety and human BD." (PMID 26190982, 2015).